FGF21 (fibroblast growth factor 21)
Diseases named in the same sentence as FGF21 in open-access papers (continued):
Sharing a sentence is not in itself a finding about the gene and the disease.
retinopathy (12 papers, 2014 to 2026). "Whether FGF21 is closely associated with the pathology of retinopathy in diabetic patients remains unclear." (PMID 24895642, 2014). "We therefore concluded that APN is a key mediator for FGF21 to improve the physiological retinal vascularization in early retinopathy." (PMID 36943533, 2023). "We have previously shown that FGF21 promotes normal retinal vessel growth in mice with oxygen-induced retinopathy where hyperoxia suppresses retinal vascular development (Phase I retinopathy)." (PMID 36943533, 2023). "In hyperglycemic mouse pups with suppression of physiological vascular development (modeling Phase I retinopathy), there were decreased retinal and liver mRNA expressions of Fgf21, similar to failed FGF21 induction in preterm infants immediately after birth (who are commonly hyperglycemic)." (PMID 36943533, 2023). "Our data suggest that increasing FGF21 levels in the presence of adequate enteral lipids may help prevent Phase I retinopathy (and therefore prevent neovascular disease)." (PMID 36943533, 2023). "On top of that, we showed that pemafibrate showed therapeutic effects against pathological neovascularization in a murine model of oxygen-induced retinopathy and rescued retinal function in streptozotocin-induced diabetic mice through increasing FGF21 levels in the blood." (PMID 34502311, 2021). "Previously, FGF21 showed therapeutic effects on several models of retinopathies in mice." (PMID 33799938, 2021). "This seems to support the conclusion that NAFLD is negatively correlated with DR, as the increased level of FGF21 may be the reason of the lower morbidity of retinopathy in patients with NAFLD after compromising with FGF21 resistance." (PMID 35004861, 2021). "Long-acting FGF21 may help reduce retinal vascular leakage in retinal disorders and machine learning assessment can help to standardize vascular leakage quantification." (PMID 32054022, 2020). "Several studies have shown that FGF21 has therapeutic effects on retinopathies in mice." (PMID 33086679, 2020). "Moreover, based on ROC model, 71.1 % accuracy was calculated for serum levels of FGF21 in the identification of patients with retinopathy." (PMID 29285020, 2017). "Since the association between serum FGF21 levels and retinopathy is not clear, this study was conducted to investigate this association." (PMID 29285020, 2017). "In our study, comparison of serum FGF21 levels among healthy controls, diabetic patients without retinopathy and patients with DR showed a significant difference." (PMID 29285020, 2017). "Findings of the present study indicated that serum FGF21 levels were significantly higher in diabetic patients compared to the control group, but difference in serum FGF21 levels was not significant between two diabetic groups with and without retinopathy." (PMID 29285020, 2017). "The result of the Kruskal-Wallis test showed a significant difference between serum FGF21 levels of the controls and diabetic patients with and without retinopathy (P=0.003)." (PMID 29285020, 2017). "Serum levels of FGF21 showed a significant difference between the three groups (P=0.003) but the difference between diabetic patients with and without retinopathy was not significant (P=0.122)." (PMID 29285020, 2017). "Serum levels of FGF21 were similar in diabetic patients without retinopathy and control group (P=0.112)." (PMID 29285020, 2017). "The major finding in the present study was that serum concentrations of FGF21 were increased in diabetic patients but nonproportional to the severity of retinopathy." (PMID 24895642, 2014). "The positive relationship between FGF21 concentration and retinopathy observed in this study was not accompanied by any obvious difference between the retinopathy subgroups with respect to factors promoting microangiopathy." (PMID 24895642, 2014).
retinopathy (continued). "In the study of Lin and colleagues, mean serum levels of FGF21 in the control group, diabetic patients without retinopathy, patients with non-proliferative retinopathy, and patients with proliferative retinopathy were respectively 125.9, 326.8, 631.9, and 669.4 pg/mL, respectively." (PMID 29285020, 2017). "However, the FGF21 difference between the two groups of diabetic patients with and without retinopathy was not significant." (PMID 29285020, 2017). "However, in their study, serum levels of FGF21 was significantly lower in type 2 diabetic patients without retinopathy than the patients with DR and according to the regression model, FGF21 was predictive of increasing DR risk after adjustment for triglycerides levels and disease period." (PMID 29285020, 2017). "In addition, as a case-control design was used for the study used, it is not easy to accurately predict whether the high FGF21 concentrations preceded the retinopathy or vice versa." (PMID 24895642, 2014). "Serum FGF21 concentrations in patients with PDR (n = 49; 669.4 ± 89.2 pg/mL) or NPDR (n = 34; 631.9 ± 73.8 pg/mL) were significantly higher than those in patients without retinopathy (n = 34; 326.8 ± 81.6, P < 0.001)." (PMID 24895642, 2014).
neurodegenerative disease (11 papers, 2020 to 2025). A disorder of the central nervous system characterized by gradual and progressive loss of neural tissue and neurologic function. "Our findings provide insights into the mechanisms underlying the effects of FGF21 on neurodegeneration and brain energy metabolism and suggest that FGF21 may have therapeutic value in the treatment of AD and other neurodegenerative diseases." (PMID 32724479, 2020). "Our findings provide insights into the mechanisms underlying the actions of FGF21 on neurodegeneration and brain energy metabolism, and suggest that FGF21 may have potential therapeutic value in the treatment of AD and other neurodegenerative diseases." (PMID 32724479, 2020). "Of note, FGF21 has been proposed as a potential early CNS biomarker in other animal models of neurodegenerative disease." (PMID 40788112, 2025). "It has been shown that FGF21 exhibits neuroprotective effects against numerous neurodegenerative diseases." (PMID 40172524, 2025). "FGF21 also attenuates neuroinflammation and promotes neurogenesis in various neurodegenerative diseases including AD and PD." (PMID 40172524, 2025). "The neuroprotective effects of FGF21 have been shown to be of clinical value in treating neurodegenerative disease." (PMID 37334756, 2023). "As far as FGF21 in AD patients, it has been reported that higher levels of FGF21 have beneficial effects in several pathologies, including neurodegenerative diseases, although the biological function of FGF21 on AD is still largely unclear." (PMID 33131010, 2021). "However, disruption of BBB integrity in neurodegenerative diseases facilitates the entry of FGF21 into CNS." (PMID 40172524, 2025). "By analogy with the amyloid-tau-neurodegeneration (A/T/N) classification in neurodegenerative diseases, a similar approach could be considered for mitochondriopathies, including biomarkers for metabolic disturbance (FGF21), apoptosis/cellular stress (GDF15) and lysosomal dysfunction (CHIT1)." (PMID 39891741, 2025). "Therefore, metabolic regulatory molecules such as insulin, glucagon-like peptide 1 and fibroblast growth factor 21(FGF21) may represent potential pharmacotherapies for neurodegenerative diseases." (PMID 37910178, 2024).
liver (6 papers, 2019 to 2024). "HDAC3 inhibitors can also mitigate diabetic liver injury by upregulating nuclear factor erythroid 2‐related factor 2 (Nrf2), and alleviate T2D‐induced aortic fibrosis and inflammation by enhancing fibroblast growth factor 21 (FGF21) synthesis." (PMID 38405061, 2024). "Additionally, serum FGF-21 levels in fatty liver or diabetic patients were higher than those in the participants in the NC group, with a negative correlation with serum HDL and a positive correlation with BMI and serum TG." (PMID 37070097, 2023). "The FGF21 response and its relation to hepatic bile acid homeostasis are described for the first time in the present study in an alcohol-induced acute-on-chronic liver injury model, which has previously been described by our group." (PMID 34360670, 2021).
neurological diseases (4 papers, 2014 to 2025). "In the future it would be interesting to study the potential benefits can be afforded by FGF21 in different neurological disorders." (PMID 25932355, 2014). "However, studies on neurological diseases have paid little attention to the effects and detailed mechanisms of FGF21 in astrocytes." (PMID 40021824, 2025). "However, studies on neurological diseases have paid little attention to the effects and detailed mechanisms of FGF21 in astrocytes, and the potential efficacy of FGF21 on astrocytes under normal and ischemic conditions is still unclear." (PMID 40021824, 2025). "For example, FGF21 has been proposed as an early biomarker of dysregulated neuronal mitochondrial dynamics and endoplasmic reticulum (ER) stress conditions that could act on oligodendrocyte precursor cells (OPCs) and promote remyelination in neurological disorders." (PMID 40021824, 2025).
neuromuscular disease (4 papers, 2020 to 2025). "It is worth mentioning that, beyond exercise, the blood levels of GDF15 and FGF21 are also increased in pathological contexts, such as in patients affected by neuromuscular diseases caused by mitochondria DNA mutations." (PMID 33329017, 2020). "In conclusion, serological assessment in a large cohort of patients with neuromuscular diseases suggests that CHIT1 levels are significantly elevated in mitochondriopathies and may complement the established biomarkers FGF21 and GDF15." (PMID 39891741, 2025).
bacterial infection (2 papers, 2024 to 2025). "A silk fibroin hydrogel co-delivering FGF21 and H2S enables staged regulation, with early H2S release reducing inflammation and bacterial infection, followed by sustained FGF21 release to promote angiogenesis and M2 polarization." (PMID 41459510, 2025).
brain diseases (2 papers, 2016 to 2019). "Nevertheless, our data and these researches strongly imply the therapeutic value of FGF21 in brain diseases with severe BBB disruption." (PMID 30842736, 2019). "Our results indicate that FGF21 may be a promising therapeutic candidate for patients with hypoxia-related BBB disruption and brain diseases." (PMID 30842736, 2019).
genetic disease (2 papers, 2013 to 2025). "This is consistent with emerging studies in muscle with mitochondrial dysfunction and genetic disease indicating a possibility that FGF21 could be induced in muscle under metabolic and energy stress, which also targets the adipose tissue." (PMID 23590285, 2013).
FGF21 also shares sentences with these, for which no sentence is quoted: acute myocardial infarction (13 papers); end-stage renal disease (8); nonalcoholic fatty liver (5); Cerebral ischemia (4); hypertrophy (4); acute respiratory distress syndrome (3); amyloidosis (3); clear cell renal cell carcinoma (3); hypercortisolemia (3); left ventricular hypertrophy (3); Overweight (3); acute hepatitis B (2); acute lung injury (2); age (2); cerebral infarction (2); Chronic colitis (2); chronic hepatitis (2); hypoadiponectinemia (2); inflammation (2); iron deficiency (2); leukocytosis (2); MELAS syndrome (2); memory impairment (2); non-small cell lung carcinoma (2); Osteopenia (2); Parkinson’s (2); peripheral neuropathy (2); schizophrenia (2); spinal cord injury (2); spinal muscular atrophy (2).
A further 100 diseases each share a sentence with FGF21 in 2 papers or fewer.